NOP58 (NOP58 ribonucleoprotein)
Description:
Required for the biogenesis of box C/D snoRNAs such as U3, U8 and U14 snoRNAs. Part of the small subunit (SSU) processome, first precursor of the small eukaryotic ribosomal subunit. During the assembly of the SSU processome in the nucleolus, many ribosome biogenesis factors, an RNA chaperone and ribosomal proteins associate with the nascent pre-rRNA and work in concert to generate RNA folding, modifications, rearrangements and cleavage as well as targeted degradation of pre-ribosomal RNA by the RNA exosome. Core component of box C/D small nucleolar ribonucleoprotein (snoRNP) complexes that function in methylation of multiple sites on ribosomal RNAs (rRNAs) and messenger RNAs (mRNAs).
Synonyms: NOP5; HSPC120; NOP5/NOP58
Tractability: Small molecule: a structure with a bound ligand is known. PROTAC: UniProt records ubiquitination sites on it; ubiquitination databases record sites on it; its protein half-life has been measured.
Gene: Protein-coding gene on chromosome 2 (202,265,725 to 202,303,666, forward strand). Ensembl gene ENSG00000055044.
Subcellular location: Nucleus, nucleolus; Nucleus, nucleoplasm
Subcellular location (Human Protein Atlas): Nucleoli fibrillar center; Nucleoplasm
Pathways (Reactome):
Metabolism of RNA: Major pathway of rRNA processing in the nucleolus and cytosol; rRNA modification in the nucleus and cytosol
Metabolism of proteins: SUMOylation of RNA binding proteins
Gene Ontology:
Molecular function: ATPase binding; protein binding; RNA binding; snoRNA binding; TFIID-class transcription factor complex binding
Biological process: ribosomal small subunit biogenesis; snoRNA localization; maturation of SSU-rRNA; mRNA modification; neuron differentiation; rRNA 2'-O-methylation; rRNA processing
Cellular component: box C/D methylation guide snoRNP complex; Cajal body; fibrillar center; membrane; nucleolus; nucleoplasm; pre-snoRNP complex; small-subunit processome; sno(s)RNA-containing ribonucleoprotein complex
Genetic constraint (gnomAD): Loss-of-function variants: 23 observed, 32.76 expected, observed/expected ratio (o/e) 0.7, 90% interval 0.5 to 1. The upper end of that interval is the gene's LOEUF score, 1, which puts it in group 4 of 6, group 1 being the genes least tolerant of losing a copy. Missense variants: 351 observed, 401.86 expected, observed/expected ratio (o/e) 0.87, 90% interval 0.8 to 0.95. Synonymous variants: 142 observed, 133.85 expected, observed/expected ratio (o/e) 1.06, 90% interval 0.93 to 1.22.
Homologues: Orthologues: dog NOP58 (98% identical), pig NOP58 (97% identical), macaque NOP58 (97% identical), rat Nop58 (96% identical), mouse Nop58 (96% identical), chimpanzee NOP58 (95% identical), rabbit NOP58 (95% identical), guinea pig NOP58 (91% identical), zebrafish nop58 (77% identical), tropical clawed frog nop58 (76% identical), Drosophila melanogaster nop5 (60% identical), Caenorhabditis elegans nol-58 (51% identical). Paralogues in human: NOP56 (41% identical).
Diseases named in the same sentence as NOP58 in open-access papers:
NOP58 is named in the same sentence as 16 diseases in open-access papers, as found by Europe PMC text mining. Sharing a sentence is not in itself a finding about the gene and the disease. The quoted sentences say what the papers report.
glioma (3 papers, 2023 to 2025). A benign or malignant brain and spinal cord tumor that arises from glial cells (astrocytes, oligodendrocytes, ependymal cells). "To explore the effect of INHEG on the association between TAF15 and NOP58, we performed endogenous co-immunoprecipitation of TAF15 and NOP58 in INHEG transcriptionally activated glioma cells." (PMID 37980347, 2023). "Mechanistically, INHEG promotes the interaction between NOP58 and TAF15, a SUMO2 E3 ligase, leading to the SUMOylating of NOP58, which is crucial for snoRNP complex formation and rRNA 2’-O-methylation, leading to elevated translation of oncogenic proteins in glioma." (PMID 39937018, 2025). "Further, endogenous NOP58 sumoylation was detected in INHEG-activated glioma cells, and upregulation of INHEG increased NOP58 sumoylation." (PMID 37980347, 2023). "To verify our hypothesis, we immunoprecipitated endogenous NOP58 and performed immunoblotting with a TAF15 antibody in glioma cells." (PMID 37980347, 2023). "Immunoprecipitation of endogenous NOP58 followed by immunoblotting with SUMO2 antibody in TAF15-knockdown cells and control cells indicated that endogenous NOP58 sumoylation was reduced after treating glioma cells with TAF15-targeted siRNAs." (PMID 37980347, 2023).
hepatocellular carcinoma (2 papers, 2021 to 2025). A malignant tumor that arises from hepatocytes. "NOP58 is significantly overexpressed in CRC and hepatocellular carcinoma." (PMID 39949372, 2025).
osteosarcoma (2 papers, 2023 to 2025). A usually aggressive malignant bone-forming mesenchymal neoplasm, predominantly affecting adolescents and young adults. "In addition, the subcellular localization results for NOP58 in osteosarcoma cell lines, as reported in the HPA database, indicated that in the U2OS cell line, NOP58 protein was mainly localized in the nucleolus fibrillar center." (PMID 40369667, 2025). "These RBPs include NOP58, FAM120C, DYNC1H1, TRAP1, and LMNA, which may serve as molecular targets for osteosarcoma immune regulation." (PMID 37139238, 2023).
breast carcinoma (1 paper, 2026). "In the ebi-a-GCST90018799 cohort, genes with causal relationships to breast cancer included NOP58, OCIAD2, P4HA2, PEMT, and PNPLA2." (PMID 41424847, 2026).
colorectal cancer (1 paper, 2022). A primary or metastatic malignant neoplasm that affects the colon or rectum. "For example, long ncRNA ZFAS1 promotes snoRNA-mediated 2′-O-methylation through Nop58 recruitment and is involved in the development and prognosis of colorectal cancer." (PMID 35790714, 2022).
Hyperglycemia (1 paper, 2015). An increased concentration of glucose in the blood. "NOP58 (NOP58 ribonucleoprotein) is essential for ribosomal biogenesis, whereas an increased expression of this protein was observed in hyperglycemia-induced vascular injury." (PMID 25901992, 2015).
prostate carcinoma (1 paper, 2024). A carcinoma that arises from epithelial cells of the prostate gland. "Immunohistochemical analysis confirmed that NOP58 was significantly overexpressed in prostate cancer tissues compared to normal tissues." (PMID 39494345, 2024). "NOP58 overexpression was strongly associated with shorter overall survival (OS), progression-free interval (PFI), and disease-specific death in prostate cancer patients." (PMID 39494345, 2024). "This study highlights the novel role of NOP58 as a target of SUMOylation and its regulatory mechanisms in prostate cancer, revealing potential new molecular pathways." (PMID 39494345, 2024). "Colony formation assays further showed that NOP58 knockdown inhibited, while its overexpression promoted, colony formation, highlighting the critical role of NOP58 in prostate cancer cell growth and survival." (PMID 39494345, 2024). "The discovery of NOP58 as a key regulatory factor provides a new perspective on the biology of prostate cancer and highlights its potential as a prognostic biomarker and therapeutic target." (PMID 39494345, 2024). "NOP58 is a key regulator of prostate cancer progression through its mediation of the SUMOylation pathway." (PMID 39494345, 2024). "Additionally, double gene molecular subtype analysis with SUMO1, SUMO2, and XPO1 genes revealed survival outcome differences across molecular subtypes, further emphasizing NOP58’s critical role in prostate cancer biology and patient prognosis (Figures A1–C5)." (PMID 39494345, 2024). "Dysregulation of NOP58 expression impairs prostate cell function, suggesting that modulating NOP58 levels could be a promising strategy for improving prostate cancer treatment." (PMID 39494345, 2024). "This study highlights NOP58’s involvement in the regulation of oxidative stress, apoptosis, and proliferation in the LNCaP and PC3 prostate cancer cell lines." (PMID 39494345, 2024). "In the HPA dataset, immunohistochemical staining demonstrated a marked overexpression of NOP58 protein in prostate cancer tissues compared to adjacent non-cancerous tissues." (PMID 39494345, 2024).
testicular germ cell tumor (1 paper, 2025). A germ cell tumor arising from the testis. "This region, commonly altered in several cancer types (especially testicular germ cell tumors), contains four NMD-related genes (CWC22, SF3B1, NOP58, and FARSB)." (PMID 41023738, 2025).
tumor (6 papers, 2018 to 2024). "Specifically, NOP58 was involved in immune priming and T cell recognition, suggesting its potential role in modulating immune responses within the tumor microenvironment." (PMID 39494345, 2024). "Furthermore, He and colleagues reported that FAM83A-AS1 was expressed in HCC cells and tissues, suggesting that increased FAM83A-AS1 expression enhances tumor proliferation and migration and represses apoptosis by interacting with NOP58." (PMID 34488540, 2021). "With the online bioinformatics tool UALCAN, we analyzed NOP58 expression based on data from Clinical Proteomic Tumor Analysis Consortium (CPTAC) datasets and found that the expression of NOP58 protein was significantly upregulated in HCC tissues compared with normal liver tissues." (PMID 37891494, 2023). "Therefore, we evaluated GBM patients diagnosed with either PN or MES subtype who received chemoradiation after tumor resection in the CGGA, revealing that high INHEG or NOP58 levels portended a shorter survival within the PN and MES subgroup." (PMID 37980347, 2023). "Similar results were obtained from 30 pairs of CRC tissues and matched tumor-adjacent normal tissues, where an elevated expression of ZFAS1 in CRC tissues and a further consistently up-regulated of SNORD12C, SNORD78, and NOP58 were detected by RT-PCR and qPCR assays." (PMID 32443980, 2020).
cancer (5 papers, 2018 to 2025). A tumor composed of atypical neoplastic, often pleomorphic cells that invade other tissues. "The analysis revealed a distinct overexpression of a single isoform for several genes, namely AGBL5, BOP1, FTSJ3, LGALS1, and NOP58, suggesting a dominant role of these isoforms in the cancer phenotype." (PMID 39001461, 2024). "Dysregulation of snoRNP members including NOP58 has been widely reported in cancer, which directly contributes to the overactivated ribosome biogenesis during cancer progression." (PMID 34868230, 2021).
infection (2 papers, 2019 to 2020). The state of being infected such as from the introduction of a foreign agent such as serum, vaccine, antigenic substance or organism. "They found increased expression of genes from the box C/D snoRNO complex (NOP1, NOP58, and SIK1), which coincides with our findings, as proteins from the box C/D snoRNO complex were in greater abundance in P1, confirming involvement of ribosome biogenesis during infection." (PMID 31293987, 2019).
NOP58 also shares sentences with these, for which no sentence is quoted: lung carcinoma (2 papers); atherosclerosis (1); gastric cancer (1); lung adenocarcinoma (1); retinoblastoma (1).